BMP6 (bone morphogenetic protein 6)
Diseases named in the same sentence as BMP6 in open-access papers (continued):
Sharing a sentence is not in itself a finding about the gene and the disease.
viral hepatitis (1 paper, 2024). An acute or chronic inflammation of the liver parenchyma caused by viruses. "It is not advisable to speculate on the mutual interaction between BMP9 and viral hepatitis based on the interaction between BMP6 and viral hepatitis." (PMID 39199400, 2024).
vitamin A deficiency (1 paper, 2016). Deficiency of vitamin A due to malnutrition, malabsorption, or dietary lack. "Vitamin A deficiency (VAD) increased hepatic Bmp6 and Hfe2 mRNA levels and down-regulated hepatic Hamp, Smad7, Rarα, and intestinal Fpn1 mRNA levels compared with the control." (PMID 27551308, 2016). "Further, the vitamin A deficiency up-regulated hepatic Bmp6 and Hfe mRNA levels in relation to those of the control group and down-regulated hepatic Hamp mRNA levels, despite similar iron levels in the liver, compared to those of the control group." (PMID 27551308, 2016). "Compared to the control group, vitamin A deficiency down-regulated Hamp (2.3-fold, p < 0.001) and Smad7 (1.6-fold, p = 0.027) mRNA levels in the liver and up-regulated hepatic Hfe2 (1.2-fold, p = 0.026) and Bmp6 mRNA levels (2.0-fold, p = 0.0013)." (PMID 27551308, 2016).
tumor (63 papers, 1998 to 2026). "Recently, a report showed BMP-6 stimulates tumor-associated macrophages to produce IL-1α through a crosstalk between Smad1 and NF-kB1." (PMID 28068414, 2017). "Recently, the close association of BMP6 with progression of tumorigenesis and regulation of invasion for tumor cells has been reported." (PMID 22695536, 2012). "BMP-6 is detected in several human neoplastic epithelial cells including breast, prostate, salivary, rectal, and thyroid carcinomas, and is speculated to be closely associated with tumor metastasis." (PMID 17997862, 2007). "Among these known mediators, THBS1 and BMP6 were also found in our in vitro screen for tumor cell dormancy-inducing endothelial factors, reinforcing our confidence in the validity of our screening methodology." (PMID 41185039, 2025). "It was shown that the expression of BMP8B was significantly increased in tumour compared with normal tissues, while BMP6 and ACVRL1 were expressed at lower levels." (PMID 37333824, 2023). "While the reduction of the BMP-Smad1/5/8 axis is in line with increased levels of Erfe, we do not observe a decreased expression of BMP ligands, such as BMP2, BMP4, and BMP6, in the skeletal muscle of C26 tumor-bearing mice." (PMID 38052214, 2023). "Lower expression of BMP2 and BMP6, in the primary tumours, was correlated with poor overall survival (OS) in the RNA sequencing analysis (n=1090)." (PMID 37333824, 2023). "Significant upregulation of expression is found in genes associated with tumor cell invasion such TGFβ1, ROAR, DAB2, BMP6, NOS2, PLXN2, and CADPS, whereas TCF4 was significantly downregulated in AHCY deficient cells." (PMID 38003292, 2023). "The hASC were distinguished by the lowest BMP-2 and BMP-6 transcript levels compared to the tumour cell lines." (PMID 36139691, 2022). "BMPs required for the formation of new bone include BMP-5 and BMP-6, which are expressed by tumor cells." (PMID 36415832, 2022). "In NSCLC, BMP6 mRNA and protein expressions in tumor tissues was significantly reduced when compared with the adjacent normal lung tissues." (PMID 36532723, 2022). "As many cell types including normal and neoplastic epithelial cells as well as macrophages possess BMPR-I and -II, BMP-6 can affect both tumor cells and TAM." (PMID 33842333, 2021). "The pathway analysis showed the involvement of the selected proteins in biological processes directly associated with tumor evolution (SEMA3A, BMP6, MDK), hepatitis viral infection (ISG15), or physiological liver functions (PLTP)." (PMID 35008303, 2021). "They stated that BMP-6 (bone morphogenetic proteins-6) stimulated TAMs to produce IL-10, which then induced M2 polarization of TAMs to mediate the pro-tumor effect of BMP-6." (PMID 32228612, 2020). "Among the candidate list we identified (MMP10, IL1α, TIE1, FGF2, BMP6), IL1α has been reported to be released by both stromal cells and PC cells, and to promote tumor growth in PDAC." (PMID 33105540, 2020). "Suppression of tumor formation in skin by induction of apoptosis was reported from the overexpression of BMP-6." (PMID 24658029, 2014). "Many types of solid tumours demonstrate elevated expression levels of BMP-6, whereas other types of tumours display reduced BMP-6 expression levels." (PMID 24498236, 2014). "The lymph node metastasis was even more hypermethylated for BMP6 than the primary tumor tissue (P < 0.05)." (PMID 22695536, 2012). "The various clones formed different tumor types in nude mice but only clones that expressed high levels of BMP-6 gave bone formation." (PMID 19771160, 2009). "Although BMP-6 expression levels varied widely among tumor specimens, it was relatively higher in ER+ cases than in ER- cases." (PMID 17997862, 2007). "Given its ability to modulate inflammation, promote osteogenesis, and counter stromal support of tumor cells, BMP6 may be particularly relevant for MM patients with active bone disease and persistent stromal dysregulation, despite remission of tumor burden." (PMID 41463400, 2025).
tumor (continued). "Also, significant alterations in genes associated with tumor cell invasion were detected, such as significant upregulation of TGFβ1, ROAR, DAB2, BMP6, NOS2, PLXN2, and CADPS exhibited, and significant downregulation of TCF4." (PMID 38003292, 2023). "Furthermore, in prostate cancer, BMP-6 promotes tumor growth by inducing angiogenesis and castration resistance." (PMID 37208766, 2023). "While technically, we were unsuccessful in performing immunohistochemistry of RGMb in these biopsies, these tumors were characterized by high levels of RNF4 and BMP6 compared with non-tumor tissue, as well as higher levels of the proliferation marker Ki67 (not shown)." (PMID 36153321, 2022). "In addition to BMP4, also elevated levels of other members of the BMP-family, including BMP6 and BMP7, have been linked to increased tumor aggressiveness." (PMID 31694641, 2019). "In vitro, BMP6 has both stimulatory and inhibitory effects on tumor cells." (PMID 30534534, 2018). "Moreover, BMP6, secreted by prostate cancer cells, stimulates macrophages to produce IL-1α which in turn promotes tube formation by EC, a prerequisite for tumor neovascularization." (PMID 30534534, 2018). "BMP-6 mRNA has been declared both increased and reduced in comparison with non-tumour margins." (PMID 28733469, 2017). "Thus, the function of BMP-6 in tumours remains controversial, and BMP-6 likely exerts its function according to the specific conditions." (PMID 24498236, 2014). "As the expression of IL-6 and BMP-6 are elevated in the tumor microenvironment, these may be important factors in the evolution of castration resistant disease." (PMID 25333263, 2014). "Moreover, we identified significantly greater hypermethylation proportion of BMP6 in the lymph node metastasis than their primary tumor tissue (P < 0.05)." (PMID 22695536, 2012). "Importantly, the reverse relationship between BMP-6/E-cadherin and δEF1 expressions in cancer cell lines has been verified in clinical tumor specimens." (PMID 17997862, 2007). "Recent studies indicate that BMP-6 is closely related to tumor differentiation and metastasis." (PMID 17997862, 2007). "However, multiple studies have suggested that the absence of or decreased BMP-6 is associated with poor survival and tumor progression in breast and non-small cell lung cancers." (PMID 37208766, 2023). "We found that miR-455 and BMP6 expression was increased and GREM1 expression was decreased in liver metastase compared with primary tumor." (PMID 38970064, 2024). "Overlapping BMP6 and BMP8B expression were also evident in the GSE70951 cohort, which includes 47 paired tumours and normal breast tissues." (PMID 37333824, 2023). "Meanwhile, the expression levels of BMP6, p-ERK and P-gp proteins in tumor tissues were analyzed by immunohistochemical staining." (PMID 36532723, 2022). "In MCF-7 and MCF-7/Adr xenografts, the expression levels of BMP6, p-ERK and P-gp proteins were analyzed by immunohistochemical staining of tumor tissues, and the results were consistent with the results from in vitro study." (PMID 36532723, 2022). "The results showed that compared with MCF-7 xenografted tumors, the expression of BMP6 was down-regulated, while the expression levels of p-ERK and P-gp were up-regulated in MCF- 7/Adr tumor tissues." (PMID 36532723, 2022). "A previous study indicated that the DUB PSMD4 promotes tumor growth and chemoresistance by stabilizing the ALK2 receptor during the initiation of the BMP6 signaling pathway." (PMID 33846536, 2021). "Hepcidin gene expression correlated with BMP6 and IL6 expression, as well as tumor-infiltrating anti-cancer immune cell populations." (PMID 34277457, 2021). "These immunohistochemical data suggest that tumor cells expressing BMP5 and BMP6 induce the transformation of mesenchymal cells, which normally express BMP2 and BMP4, in preosteoblasts and osteoblasts." (PMID 25529855, 2014).
tumor (continued). "The pathway analysis revealed that BMP6, BRCA1 and P16 have a role in prevention of neoplasm metastasis." (PMID 22695536, 2012). "In conclusion, the present study showed aberrant tumor-specific methylation alterations for APC, BIN1, BMP6, BRCA1, CST6, ESR-b, GSTP1, P14, P16, P21, PTEN and TIMP3 in the studied cohort." (PMID 22695536, 2012). "Two-way hierarchical clustering in serum and tumor tissue showed significant hypermethylation patterns of seven genes (APC, BIN1, BMP6, BRCA1, CST6, P16 and TIMP3) compared with normal tissue." (PMID 21283676, 2011). "Hierarchical clustering showed significant hypermethylation patterns for serum and tumor tissue compared with normal tissue for seven genes (APC, BIN1, BMP6, BRCA1, CST6, P16 and TIMP3)." (PMID 21283676, 2011). "Over-expressing BMP-6 delays scar formation in wound healing, but stimulates fibrous encapsulating of BMP-6 over-expressing tumours." (PMID 20858224, 2010). "Additionally, these epithelial cells secrete factors such as bone morphogenetic protein 6 (BMP-6) and cyclooxygenase 2 (COX-2), which facilitate the phenotypic transition of TAMs from the antitumorigenic M1 subtype to the tumor-promoting M2 subtype." (PMID 40746825, 2025). "No obvious change was seen in the expression of BMP2 and BMP6 when the primary tumours developed distant metastases." (PMID 37333824, 2023). "In addition to these, BMP2, BMP6 and GDF5 were highly expressed in the TNBC tumours compared with tumours of other subtypes." (PMID 37333824, 2023). "In addition, hepcidin expression strongly correlated with BMP6 and IL6 genes, as well as anti-cancer immune cell populations in the tumor microenvironment." (PMID 34277457, 2021). "In a mouse model of malignant melanoma for example, the absence of BMP-6 resulted in a substantial delay in tumor onset and progression by a mechanism depending on mast cells." (PMID 33842333, 2021). "KHSRP mainly enhances tumor cell migration and invasion by promoting the maturation of miR-130b, miR-21 and miR-301a and by indirectly inhibiting the expression of their targets, such as endogenous EMT inhibitors BMP6, PDCD4 and TIMP3." (PMID 29254151, 2017). "The quantitative DNA methylation analysis of the candidate genes showed higher methylation proportion in the primary tumor tissue than that of the matched normal tissue and the differences were significant for the APC, BIN1, BMP6, BRCA1, CST6, ESR-b, P16, PTEN and TIMP3 promoter regions (P<0.05)." (PMID 22695536, 2012). "A correlation study of the methylation proportion of DNA in serum versus cancerous and normal breast tissue revealed a correlation between tumor tissue and serum for BMP6, BRCA1, CST6, GSTP1, P16 and TIMP3 genes but not with the matched normal tissue." (PMID 21283676, 2011). "Lines of evidence suggest that at early stages of carcinogenesis, BMP-6 is not a tumour promoter, but suppresses benign and malignant tumour outgrowth." (PMID 15877825, 2005). "Notably, BMP6 selectively promoted bone formation without enhancing osteoclastogenesis and attenuated inflammatory and tumor-supportive MSC phenotypes." (PMID 41463400, 2025). "Furthermore, we demonstrated that the downregulation of BMP2 and BMP6 is not tumor-subtype-specific, and the same expression pattern is present across different molecular subtypes." (PMID 38731813, 2024). "Overall, in all tumor portions of the tissue microarray (TMA) we observed higher levels of RNF4 and BMP6 compared to the non-tumor tissue." (PMID 36153321, 2022). "Among 11 BMPs, BMP3 and BMP8A expression levels were upregulated, and 5 BMPs (BMP2, BMP5, GDF5, BMP6, and GDF10) downregulated in tumor tissues compared with normal tissues." (PMID 34745928, 2021). "In this study, we have found an association between the expression of the follow proteins (STAT5, STAT3_pS727, BMP6, CD74, TFRC, INHA, and STAT5_pY694) involved in iron homeostasis and the type of tumor tissue (breast cancerous vs. non-cancerous)." (PMID 28216608, 2017).
cancer (43 papers, 2005 to 2025). A tumor composed of atypical neoplastic, often pleomorphic cells that invade other tissues. "Fluorescent labeled MDA-MB-231 cells have been microinjected into Tg (fli1:EGFP) zebrafish embryos and used to show that Smad6 and Bmp6 expression regulates cancer cell invasion and is linked to E-cadherin expression." (PMID 37048068, 2023). "Studies showed that BMP6 was associated with the occurrence and development of various malignant tumors." (PMID 36532723, 2022). "Several studies have implicated BMP-6 in the linkage of immune regulation and cancer progression." (PMID 33842333, 2021). "KHSRP knockdown also inhibited the maturation of cancer-associated miRNAs, such as miR-21, miR-130b, and miR-301, and induced the expression of their target mRNAs, such as BMP6, PDCD4, and TIMP3, resulting in the inhibition of epithelial-to-mesenchymal transition." (PMID 29254151, 2017). "Several studies have confirmed that decreased expression of BMP6 and BMP7 is associated with fibrosis and cancer cell proliferation." (PMID 39915830, 2025). "By applying the method outlined in Method 7, we have predicted BMP6, TGFα, and TGFβ1 as the growth signals specifically needed by the cancer type." (PMID 39796131, 2024). "The expression of BMP6 correlates with cancer progression and prognosis, and BMP6 is known to promote invasion and metastasis." (PMID 39796131, 2024). "Conversely, the down-regulated DEGs are linked to pathways associated with cancer or immune responses, in alignment with previous findings, such as SCD1, ELOV2, FADS1, FADS2, and BMP6." (PMID 38693536, 2024). "Previous studies showed that incubation of cancer cells with E2 induces BMP6 expression and BMP6 promoter–reporter construct activity, which is mainly mediated through ERα." (PMID 36768740, 2023). "As members of the TGF-ß superfamily of cytokines, BMP-2 and BMP-6, are specifically involved in the maintenance of iron homeostasis, yet also immune regulation and cancer progression." (PMID 33842333, 2021). "This DNA methylation signal is decreased in the BMP-6 gene body, which is consistent with the typical DNA methylation signal observed in cancer tissue." (PMID 24498236, 2014). "In contrast, we unexpectedly found that also tumors derived from the carcinoma clones, i.e. low producers of BMP-6, were positive for BMP-6 protein." (PMID 19771160, 2009). "Recent work has shown that BMP3b is epigenetically inactivated in cancer and suggests that BMP6 can be epigenetically inactivated." (PMID 16175182, 2005). "BMP6 is a member of the TGFβ superfamily and its deregulation is involved in cancer." (PMID 37667404, 2023). "Taken together, our study highlights the important roles of RNF4 and its regulated factors RGMb and BMP6 in osteogenic differentiation of mesenchymal stem cell and cancer opening the door for the development of diagnostics and specific inhibitors for the treatment of these challenging cancers." (PMID 36153321, 2022). "BMP5 and BMP6 play an important role in various cancers; both have been shown to induce apoptosis." (PMID 29986714, 2018). "Therefore, an unopposed effect of an excess of BMP-6 locally released by cancer cells is also a determinant of the osteoblast response both in CaP and CaM bone metastasis." (PMID 21249149, 2011). "In plasma samples, promoter hypermethylation of GSTP1 gene was significantly correlated with higher age (≥50), hypermethylation of P16 gene was correlated with pathologic early stage of cancer and hypermethylation of BMP6 gene was correlated with lymph node involvement (P<0.05)." (PMID 21283676, 2011). "We cannot with certainty explain this apparent discrepancy, although we favor the possibility that the BMP-6 protein expression in the carcinoma clones may have been upregulated during the in vivo inoculation process." (PMID 19771160, 2009).
cancer (continued). "Noteworthy, several candidate susceptibility genes (PRKCA, BMP6, ADAMTS19, ARHGAP6, FUT9/8, FAM108C1, CHL1, BTBD9 and WDR52) are involved in the actin cytoskeleton arrangement, cell adhesion and cell motility processes, which are important for cancer invasion and metastasis." (PMID 22532847, 2012). "For example, androgen withdrawal-induced marked downregulation of relaxin, VEGF, vimentin and BMP-6, involved in cancer progression as well as upregulation of cellular retinol binding protein 7 and interferon-γ receptor, negatively regulating cancer progression, in LNCaP/IL-6#1." (PMID 19844233, 2009). "However, under deprivation of serum, BMP-6 protects MDA-MB-231 cancer cells from stress-induced apoptosis through upregulation of survivin, via the Smad dependent pathway, and activation of p38 via the Smad-independent pathway, with both contributing to the anti-apoptotic effect of BMP-6." (PMID 28733469, 2017). "BMP-6 produced by cancer cells was able to induce mineralization of M3T3 pre-osteoblasts, and blocking BMP-6 activity reduced osteolastic lesion formation by LuCaP 23.1 cells in vivo." (PMID 25566502, 2014). "Patients who did not respond to immunotherapy had cancer tissues with elevated BMP6 and FN1 expression, in contrast to those who responded, where CD274, HOXB5, and PPIL3 were more expressed." (PMID 40642086, 2025). "BMP6 modulated VEGF signaling by regulating VEGFR2 expression and acted via Hippo signaling effector TAZ, known to regulate cell survival/proliferation, and to be dysregulated in cancer." (PMID 33021694, 2021). "Unexpectedly, tumors from scirrhous carcinoma clones, i.e. clones showing low levels of BMP-6 mRNA expression in vitro and a low degree of Smad-1/5 pathway activation, were strongly positive for BMP-6 protein." (PMID 19771160, 2009). "The morphogenetic BMP signaling (BMP6 and INHA), the pro-inflammatory JAK/STAT pathway and CD74, a pro-inflammatory component in terms of infiltrating macrophages, resulted in discriminating between cancer and non-cancer samples." (PMID 28216608, 2017).